RNU4-46P (RNA, U4 small nuclear 46, pseudogene)
Gene: Small nuclear RNA gene on chromosome 16 (19,498,610 to 19,498,747, forward strand). Ensembl gene ENSG00000222750.
Homologues: Orthologues: chimpanzee U4 (100% identical), macaque U4 (96% identical), mouse Gm23429 (70% identical). Paralogues in human: RNU4-49P (79% identical), RNU4-52P (79% identical), RNU4-66P (78% identical), RNU4-51P (77% identical), RNU4-43P (75% identical), RNU4-10P (74% identical), RNU4-81P (72% identical), RNU4-32P (71% identical), RNU4-50P (70% identical), RNU4-24P (69% identical), RNU4-17P (67% identical), RNU4-40P (66% identical), and 81 more.